BGN (biglycan)
Diseases named in the same sentence as BGN in open-access papers (continued):
Sharing a sentence is not in itself a finding about the gene and the disease.
prostate carcinoma (22 papers, 2014 to 2026). A carcinoma that arises from epithelial cells of the prostate gland. "Recent studies in human prostate cancer showed that upregulation of BGN was associated with tumor progression and poor prognosis, indicating that it serves as a marker to determine the aggressiveness of prostate cancer." (PMID 35053617, 2022). "Indeed, poor prognosis in prostate cancer has been linked to elevated biglycan and syndecan-1." (PMID 32354091, 2020). "Some researchers have pointed out that upregulation of biglycan is associated with a poor prognosis and PTEN deletion in prostate cancer." (PMID 37394064, 2023). "VCAN has been shown to be up-regulated in prostate cancer along with the PGs syndecan-1, perlecan, decorin, biglycan, neural/glial antigen, serglycin and lumican." (PMID 32354091, 2020). "Several proteoglycans have been found to be important in prostate cancer, including versican, decorin, biglycan, lumican, and syndecan-1, and data from a range of studies implicate proteoglycan alterations to prostate cancer cell survival and metastasis." (PMID 30893936, 2019). "For example, an expression of collagens I, II, III, IV, fibromodulin, and proteoglycans (decorin, biglycan, lumican) in stromal cells, when grown in the presence of two metastatic prostate cancer cell lines PC3 and DU145, is significantly down-regulated." (PMID 24782989, 2014). "In prostate cancer, PGs have been shown to be involved in many steps of its progression; the most prominent examples include the seemingly tumor-promoting roles of versican, perlecan, and biglycan, and the tumor-suppressive roles of decorin and betaglycan." (PMID 41470114, 2025). "This may provide a continuing impetus for the invasion and metastasis of prostate cancer during the androgen deprivation stage, and high expression of BGN may indicate that prostate cancer has evolved into CRPC or metastasized." (PMID 34722497, 2021). "Other PGs may also play a role, particular those that are up-regulated in prostate cancer, such as syndecan-1, perlecan, decorin, biglycan, neural/glial antigen 2, serglycin and lumican." (PMID 32354091, 2020). "Previous studies have shown that ING3 promotes prostate cancer growth by activating the androgen receptor, and PHF20 promotes glioblastoma cell malignancies through a WISP1/BGN‐Dependent pathway." (PMID 39538416, 2024). "Unlike the other class I SLRPs (decorin and biglycan), asporin contains a unique and conserved stretch of aspartate (D) residues in its N terminus, and germline polymorphisms in the D-repeat-length are associated with osteoarthritis and prostate cancer progression." (PMID 31608236, 2019).
atherosclerosis (20 papers, 2007 to 2025). A disease characterized by the build-up of fatty material and calcium deposition in the arterial wall resulting in partial or complete occlusion of the arterial lumen. "Loss of biglycan led to enhanced thrombin generation and platelet activation in ApoE-deficient mice, suggesting a role for biglycan in inflammation and atherosclerosis." (PMID 34830059, 2021). "Early stage of atherosclerosis has been associated with an accumulation of biglycan." (PMID 32635482, 2020). "The role of proteoglycans was demonstrated recently in a human pathology study in coronary arteries in which it was shown that atherosclerosis commences with the deposition lipoproteins associated with the expression of biglycan in the outer layer of the diffuse intimal thickenings." (PMID 17963526, 2007). "This lipid retention occurs primarily in the deep intima based on the charge-charge interaction between apoB and biglycan and decorin secreted in high amounts by SMCs in this region, and prior to any significant monocyte infiltration in human atherosclerosis." (PMID 35795646, 2022). "Based on studies, retention of LDL on hyper-elongatedGAG chains on proteoglycans such as biglycan resultsin increased foam cell formation and progressionof arterial wall atherosclerosis." (PMID 34837677, 2021). "It has also been shown that biglycan impedes progression of atherosclerosis by mitigating thrombin activities and inflammation, suggesting that this factor can have other systemic actions." (PMID 28209124, 2017). "We have studied the effect of GKA on proteoglycan, specifically biglycan synthesis, which was used as a model for the initiation of atherosclerosis." (PMID 24731772, 2014). "However, some investigations suggest contradictory SLRP-related cardiovascular effects, e.g., BGN has been reported to contribute to cardiac hypertrophy and fibrosis, as well as atherosclerosis." (PMID 38786104, 2024). "A process of compensation (or redundancy) displayed by other PGs expression in the present model could explain the absence of a SDC-1 specific effect, as it has been reported in the context of atherosclerosis between biglycan and perlecan for Apo-B retention." (PMID 35548440, 2022). "Biglycan has been regarded as the inducer of vascular remodeling in atherosclerosis." (PMID 32635482, 2020). "Biglycan, one of the candidate ECMs known to be involved in pro-inflammatory events such as atherosclerosis, induced a more migratory phenotype by altering the cell shape and increasing the expression of several effectors genes that are involved in cell migration." (PMID 24736499, 2014). "In this regard, recent observations have shown that the initial entrapment of LDL within the extracellular matrix depends on interaction of LDL with biglycan and versican and atherosclerosis-prone arteries, such as the coronary artery, have a thickened intima enriched in versican and biglycan." (PMID 24358251, 2013). "The retention of lipoproteins by biglycan is established as a mechanism leading to atherosclerosis." (PMID 22374465, 2012). "Similarly, biglycan has been shown to be protective in a mouse model of atherosclerosis, where APOE-deficient mice, also deficient in biglycan, displayed enhanced circulating thrombin levels, elevated platelet activation and increased adhesion in vivo compared to control APOE knockouts." (PMID 38256024, 2024). "Furthermore, overexpression of biglycan in mice increased atherosclerosis." (PMID 37511353, 2023). "In addition to its detrimental roles in obesity, BGN also influences atherosclerosis development." (PMID 32508807, 2020). "Biglycan is found in the ECM of arterioles and capillaries and is important for thrombin generation upon inflammation and atherosclerosis." (PMID 34830059, 2021).
atherosclerosis (continued). "Thus, the binding of biglycan DS to TG2 that promotes the positioning of the enzyme in crucial ECM sites may play a significant role in the regulation of matrix modification in the course of wound healing, fibrosis, atherosclerosis or small artery remodeling." (PMID 28199387, 2017).
melanoma (18 papers, 2012 to 2026). A malignant, usually aggressive tumor composed of atypical, neoplastic melanocytes. "While the function of biglycan (BGN) is recognized in various cancers, its precise role and the mechanisms underlying cancer-associated fibroblasts (CAFs) formation within the melanoma tumor microenvironment (TME) remain poorly understood." (PMID 41833003, 2026). "Biglycan-deficient fibroblasts generate a less rigid matrix, with decreased expression of integrin-β1 and, consequently, a reduced capability to promote melanoma cell invasion." (PMID 34067929, 2021). "Increased production of ECM proteins, such as gamma 2 chain of laminin 5 (laminin 5 γ2), hyaluronan, collagen I, biglycan, tenascin-C and fibronectin are associated with melanoma progression." (PMID 34067929, 2021). "In melanoma models, the loss of biglycan expression in mouse embryonic fibroblasts results in softer ECM with less collagen crosslinking and reduced collagen fiber density." (PMID 33330449, 2020). "In conclusion, the interplay between cancer cells and CAFs mediated by the BGN/MDK axis is a critical driver of malignancy in melanoma, highlighting it as a promising therapeutic target for intervention." (PMID 41833003, 2026). "Strikingly, there is a growing body of evidence from mouse studies and melanoma patient data that increased Biglycan levels promotes melanoma metastasis, drives tumour angiogenesis and correlate with poor patient outcomes." (PMID 40654904, 2025). "Biglycan expression in melanoma promotes the formation of a denser collagen architecture leading to increased tissue stiffness." (PMID 36693448, 2023). "Biglycan-induced tissue stiffness in turn upregulates β1 integrin expression and promotes the invasion of melanoma cells." (PMID 36693448, 2023). "In conclusion, we reported the association of HRGs with patient prognosis in melanoma and screened for novel gene signatures, including FBP1, NDRG1, GPI, IER3, B4GALNT2, BGN, PKP1, and EDN2." (PMID 37422626, 2023). "Biglycan in fibroblasts promotes melanoma invasiveness via increased tissue stiffness, thereby inducing integrin-β1 expression, which is supported by our findings." (PMID 33966638, 2021). "The overexpression of biglycan is able to increase the number of metastasis in endometrial cancer and melanoma mice models, mainly due to an increase in the angiogenic capacity of tumor endothelial cells." (PMID 33809543, 2021). "It has been previously demonstrated that biglycan expression is involved in matrix contraction and increased in matrix stiffness which induce β1 integrin expression, promoting invasion of melanoma cells." (PMID 32984031, 2020). "Regarding melanoma, tenascin C and fibronectin affect the organization of collagen fibers and biglycan is involved in matrix contraction and increased matrix stiffness." (PMID 32984031, 2020). "We observed that the extracellular matrix molecule biglycan (Bgn) was expressed in certain human melanoma cells and primary fibroblasts when evaluated by microarray-based gene expression analysis." (PMID 28476030, 2017). "We have reported that biglycan expression in TECs is not limited to murine melanoma models but is also found in several other human solid tumours such as lung cancer and renal cancers." (PMID 27295191, 2016). "Furthermore, it has been reported that the expression of biglycan, an important and abundant component of melanoma microenvironment, stimulates the formation of a dense collagen matrix, characterized by increased stiffness." (PMID 34067929, 2021). "In melanoma, biglycan results in stromal stiffness and integrin activation." (PMID 32821344, 2020). "High biglycan expression has been shown to promote invasiveness of melanoma cells." (PMID 32984024, 2020). "Consequently, BGN significantly promoted melanoma proliferation and metastasis." (PMID 41833003, 2026). "For example, in melanoma, resistance against BRAF-inhibitor was accompanied by increased ECM levels of versican and biglycan." (PMID 33330449, 2020).
melanoma (continued). "We observed that the genes DCN (decorin), LUM (lumican) and BGN (Bgn), which are members of the small leucine-rich proteoglycan (SLRP) family, were within the highest expressed ECM genes in both melanoma cells and fibroblasts." (PMID 28476030, 2017). "We discovered that N6-methyladenosine (m6A) modulators-specifically YTHDF3, YTHDC1, and METTL14-cooperatively upregulate BGN expression in a parallel, non-hierarchical manner converging on functional m6A sites within melanoma cells." (PMID 41833003, 2026). "Not only BGN, but also PRELP has a positive immune modulatory potential by increasing the expression of HLA class I APM and IFN-γ signaling components suggesting a tumor suppressive activity of PRELP in melanoma." (PMID 37730606, 2023). "Biglycan expression is either absent or undetectable in several human tumour cell lines including the epithelial carcinoma cell line A431, pancreatic adenocarcinoma cell line Miapaca2 and melanoma cell line A375SM (data not shown)." (PMID 22374465, 2012).
bladder cancer (17 papers, 2013 to 2024). "BGN is also significantly correlated with EMT gene signatures in bladder cancer, and EMT is closely associated with BGN-driven oncogenesis." (PMID 39578715, 2024). "The present study reveals for the first time that BGN expression was associated with higher tumor stages (T- and G-staging) in human bladder cancer specimens." (PMID 24223213, 2013). "The results from human bladder cancer samples suggested that BGN expression associated with tumor progression." (PMID 24223213, 2013). "Deduced from this analysis it appears that high BGN mRNA expression is associated with increased survival of bladder cancer patients." (PMID 24223213, 2013). "Furthermore, BGN has been implicated in various tissue specific oncogenesis such as pancreatic, gastric, endometrial, colon and bladder cancer." (PMID 35053617, 2022). "In addition, BGN has been implicated in various tissue-specific tumorigenesis, such as pancreatic, gastric, endometrial, colon, and bladder cancers." (PMID 36510567, 2022). "Taken together, this study provides first evidence that BGN (i) is associated with high grade human bladder cancer, (ii) inhibits bladder cancer cell proliferation and progression of experimentally induced xenograft tumors in mice and (iii) is induced by multi-kinase inhibitors." (PMID 24223213, 2013). "BGN inhibition in bladder cancer enhanced proliferation of tumor cells demonstrating that BGN acts as a tumor suppressor." (PMID 35053617, 2022). "For instance, in bladder cancer, it was demonstrated that high levels of biglycan predict poor prognosis of patients, while other studies correlated high levels of BGN mRNA with a favorable patient’s prognosis." (PMID 33809543, 2021). "BGN was indicated to be an endogenous inhibitor of bladder cancer cell proliferation by antiproliferative tyrosine kinase inhibitors." (PMID 33193589, 2020). "For this purpose tumor biopsies of 76 bladder cancer patients with different tumor stages (pTa, pT1-T4) were investigated with respect to biglycan expression and correlated with a long-term (10 years) clinical follow-up." (PMID 24223213, 2013). "Future studies on larger patient cohorts have to further assess the prognostic value of BGN expression in bladder cancer." (PMID 24223213, 2013). "Based on our results, biglycan expression is detected in human bladder cancer cells which lack decorin expression." (PMID 24146840, 2013). "Aim of this study was to assess for the first time the expression and role of BGN in patients with bladder cancer." (PMID 24223213, 2013). "In this regard it is very interesting that in vitro treatment of human bladder cancer cells with multi-kinase inhibitors sorafenib and sunitinib resulted in a strong up-regulation of BGN as presented here." (PMID 24223213, 2013). "The therapeutic exploitation of the potentially inhibitory effects of BGN in bladder cancer is likely impeded by the fact that BGN mimetic strategies are not available." (PMID 24223213, 2013). "In conclusion, the present data suggest that biglycan is an endogenous inhibitor of bladder cancer cell proliferation that is upregulated in response to anti-proliferative tyrosine kinase inhibitors." (PMID 24223213, 2013). "If the same applies also for bladder cancer cells, it is conceivable that BGN serves as an inhibitor of tumor progression by P2X7-mediated signals." (PMID 24223213, 2013). "First, the samples of 76 patients with different stages of bladder cancer were analyzed with respect to BGN mRNA expression and compared to the expression in healthy bladder tissue." (PMID 24223213, 2013). "It is known that BGN modulates several pathways that are of relevance for bladder cancer progression such as the Wnt/β -catenin pathway, the TGFβ signaling, inflammatory signaling through TLR receptors and the P2X7 receptor." (PMID 24223213, 2013).
bladder cancer (continued). "Surprisingly, subsequent in vitro results in human bladder carcinoma cells revealed that knock-down of BGN accelerated proliferation of cancer cells." (PMID 24223213, 2013). "Since in this study BGN expression was experimentally targeted only in tumor cells, it can be concluded that tumor cell-derived BGN is a growth inhibitor of bladder carcinoma cells." (PMID 24223213, 2013). "Thus, both SLRPs, decorin and biglycan, appear to be inhibitory but are differentially regulated in bladder cancer." (PMID 24223213, 2013). "Interestingly, significant differences were detected in mRNA expression levels with respect to tumor invasiveness, grading and staging, suggesting increased BGN mRNA in progressed stages of bladder cancer." (PMID 24223213, 2013). "Furthermore, addition of recombinant BGN and ectopic overexpression of BGN suppressed bladder cancer cell growth." (PMID 24223213, 2013). "In line with the hypothesis that BGN is an endogenous inhibitor of bladder cancer progression, Kaplan-Meier analysis revealed improved cancer-specific survival in patients with high BGN mRNA expression." (PMID 24223213, 2013). "Therefore, it is conceivable that the induction of BGN contributes to the potential anti-tumor effects of sorafenib and sunitinib in bladder cancer." (PMID 24223213, 2013). "Finally, to set the basis for an in vivo xenograft experiment and to unravel the role of endogenous BGN, lentiviral knock-down of BGN was performed in the human bladder cancer cell line, J82." (PMID 24223213, 2013). "The SLRP decorin, which is closely related to BGN, has recently been studied in bladder cancer." (PMID 24223213, 2013). "Similarly, treatment with exogenous biglycan of bladder cancer cells inhibits cell proliferation and high biglycan levels correlate with prolonged survival of bladder cancer patients, and superior patient prognosis of patients with diffuse large B-cell lymphoma." (PMID 34917515, 2021). "Therefore, it was hypothesized that BGN up-regulation in human bladder cancer tissue is part of an endogenous control mechanism to limit tumor growth." (PMID 24223213, 2013). "In contrast, IHC analysis of the samples for another small leucine-rich proteoglycan, namely biglycan, revealed that decorin negative areas in invasive bladder cancer tissue were positive for biglycan immunoreactivity." (PMID 24146840, 2013). "As Wnt/β-catenin signaling is known to support tumor progression in a variety of tumors including bladder cancer, the activation of this pathway is unlikely to be responsible for the anti-proliferative effect of BGN in the present study." (PMID 24223213, 2013).